TSLIG3C (tRNA splicing ligase complex subunit 3C)
Synonyms: FAM98C; FLJ44669
Tractability: PROTAC: ubiquitination databases record sites on it; its protein half-life has been measured.
Gene: Protein-coding gene on chromosome 19 (38,403,093 to 38,409,088, forward strand). Ensembl gene ENSG00000130244.
Subcellular location (Human Protein Atlas): Nucleoli; Nucleoplasm; Cytosol
Gene Ontology:
Molecular function: protein binding
Cellular component: tRNA-splicing ligase complex
Genetic constraint (gnomAD): Loss-of-function variants: 38 observed, 36.22 expected, observed/expected ratio (o/e) 1.05, 90% interval 0.81 to 1.38. The upper end of that interval is the gene's LOEUF score, 1.38, which puts it in group 5 of 6, group 1 being the genes least tolerant of losing a copy. Missense variants: 493 observed, 427.67 expected, observed/expected ratio (o/e) 1.15, 90% interval 1.07 to 1.24. Synonymous variants: 195 observed, 181.94 expected, observed/expected ratio (o/e) 1.07, 90% interval 0.95 to 1.21.
Homologues: Orthologues: chimpanzee FAM98C (99% identical), macaque FAM98C (93% identical), pig FAM98C (79% identical), mouse Fam98c (73% identical), rat Fam98c (72% identical), zebrafish fam98a (36% identical), Drosophila melanogaster CG5913 (27% identical), Caenorhabditis elegans tag-322 (24% identical). Paralogues in human: TSLIG3A (39% identical), TSLIG3B (35% identical).
Diseases named in the same sentence as TSLIG3C in open-access papers:
TSLIG3C is named in the same sentence as 2 diseases in open-access papers, as found by Europe PMC text mining. Sharing a sentence is not in itself a finding about the gene and the disease.
TSLIG3C shares sentences with these, for which no sentence is quoted: ciliopathy (1 paper); colorectal cancer (1).